STAT3 (signal transducer and activator of transcription 3)
Diseases named in the same sentence as STAT3 in open-access papers (continued):
Sharing a sentence is not in itself a finding about the gene and the disease.
infection (continued). "In addition to STAT3, STAT4 signaling via IL-12 may also promote early Tfh progenitor cells during infection and appears to be critical for the differentiation of human Tfh cells." (PMID 25569154, 2015). "A strong impact of antimicrobials induced by Stat3 activation on the gut flora is also supported by our study as unlike control mice, C. rodentium sensitive Stat3ΔIEC mice showed no induction of RegIIIγ, RegIIIβ and Pla2g2a after infection." (PMID 25799189, 2015). "Interestingly, our data showed up-regulation of both STAT1 and STAT3 in the Hep-dG infection group, but not in rHep-Flury-infected cells." (PMID 26217322, 2015). "Moreover, during infection, transcriptional activation of CCR5 was mostly dependent on STAT3." (PMID 24695099, 2014). "Whereas, this reduced collagen I content could not be detected in infected STAT3 KO mice 28 days after infection." (PMID 22675647, 2012). "Interestingly, this inhibition of ECM degradation was still demonstrated in infected STAT3 KO mice 28 days after infection but was not longer determined in infected WT animals." (PMID 22675647, 2012). "There, no viral genome was detected in infected wild-type or STAT3 KO mice 28 days after infection." (PMID 22675647, 2012). "Because ROP16 deletion did not completely abrogate STAT3 tyrosine phosphorylation, we examined whether the active transcription factor translocated to the nucleus during infection with ROP16 knockout parasites." (PMID 21931552, 2011). "Since STAT3 is activated, we expected to detect differential expression of STAT3 target genes; however, other STAT proteins activated by E. chaffeensis, such as STAT5 and STAT6, also mediate inflammatory and oncogenic signaling and may be relevant during infection." (PMID 41115066, 2025). "Notably, the genes induced by the infection were enriched in multiple immune activation pathways, including cytokine-cytokine receptor interaction (e.g., Il22, Tnfrsf9 and Clcf1), JAK-STAT signaling pathway (e.g., Stat3), and chemokine signaling pathway (e.g., Ccr7) 33–35." (PMID 39013884, 2024). "While STAT3 signaling is of demonstrable importance to HHV-8 latent and lytic biology, it seems reasonable to hypothesize that there are mechanisms by which this signaling can be attenuated and fine-tuned to achieve optimal conditions for both phases of infection." (PMID 37983265, 2023). "Thus, the roles of BLP in the activation of the STAT3, MAPK, and NF-κB signaling pathways in macrophages after stimulation with LPS (1 μg/mL) and BLP (1 μg/mL) alone or in combination, E. coli DH5α (MOI 5:1), or E. coli JE5505 (multiplicity of infection [MOI], 5:1) were examined by Western blotting." (PMID 36916913, 2023). "T. gondii possesses effector proteins that act on host cells, which are capable of inducing the activation of the STAT3, STAT6, and NF-κB pathways, thus leading to the production of many cytokines and immunomodulatory molecules that may interfere in infection latency." (PMID 31828046, 2019). "Furthermore and as previously shown, infection of cultured cells did not alter the endogenous levels of other signaling components including Erk, cJun, p38, or STAT3, which are robustly activated by S. Typhimurium." (PMID 26933955, 2016). "Finally, it is interesting to note that STAT3-dependent cytokines, such as IL-6, IL-10, and IL-21, as well as MyD88-dependent IL-1 have been suggested to play a role in memory CD8+ T cell differentiation and functional maturation following immunization and infection." (PMID 24842874, 2014).
infection (continued). "Interestingly, the significantly reduced infiltration of Mac3+ cells in cardiac tissue of CVB3-infected WT comparing day 10 and 28 after infection could not be demonstrated in the cardiac tissue of infected STAT3 KO mice." (PMID 22675647, 2012). "In addition, in the JIMT-1 CD44−/CD24− non-CIC population expression of both STAT1 and STAT3 decreased 60 min after infection and no more P-STAT3 could be detected at this time point." (PMID 21079774, 2010). "By enhancing interstitial macrophages’ capacity to degrade pathogens while restraining STAT3/PI3K‐driven inflammation, punicalagin resists infection without exerting direct bactericidal effect." (PMID 41085014, 2026). "In this study, we observed that cryptotanshinone, an inhibitor of STAT3, but not STAT5-IN-1, an inhibitor of STAT5, impeded the proliferation of EBV-infected B-cell colonies at an early stage of infection both in the absence and presence of hrGal-9 protein." (PMID 36622166, 2023). "Phosphorylated STAT3 is a part of the IL6-STAT3 inflammatory pathway and STAT3 phosphorylation is increased upon infection with S.Tm and E.coli but is not affected by either osH or LDN." (PMID 34368018, 2021). "The up-regulation of STAT3 phosphorylation due to the TLT2 overexpression following BCG and H37Rv infection was absent in the overexpression of TLT2 single Y297F or Y315F mutant and Y297/315F double mutant in the THP-1 cells." (PMID 33042115, 2020). "Type I or III ROP16 can phosphorylate and activate STAT3 and STAT6 during infection, whereas type II ROP16 does not have this effect." (PMID 32012177, 2020). "In our study, phosphorylation of STAT3 and STAT6 transcription factors after infection with T. gondii RH or RHΔrop16 was not different between the OT and Asym groups." (PMID 31867288, 2019). "STAT3 also partially contributed to EHDV-TAU-induced oncolysis in the presence of IL-6, which occurs in the absence of productive infection." (PMID 29441069, 2018). "Interleukin 6 (IL-6) is a classic proinflammatory cytokine that signals through STAT3 as part of the acute phase response (APR), a nonspecific reaction of the innate immune system to pathogen infection." (PMID 29543893, 2018). "The infection of cells with aNSa1, VHL-aNSa1, aCS3 and VHL-aCS3 did not alter the levels of phospho-STAT3-Tyr705 or phospho-STAT5-Tyr694." (PMID 28490657, 2017). "In contrast to infection with UV-HCMV, ganciclovir pretreatment of the cells did not prevent STAT3 activation in PHH infected with HCMV, indicating that STAT3 activation, like IL-6 production, did require early steps of viral replication." (PMID 23555719, 2013). "However, H. pylori infection did not further enhance STAT3 activation, suggesting that STAT3 signaling may be involved in the pathology observed in Rnf43 mutant mice already under basal conditions, and may favor enhanced pathology upon infection by crosstalk with other signaling pathways." (PMID 30884828, 2019). "Similarly, phosphorylated forms of STAT3 and TAK1, detected in keratinocyte cytosol 3 hours post-infection, were reduced by filaggrin-specific siRNA but not control siRNA." (PMID 28081250, 2017). "Interestingly, in infected STAT3 KO mice, TGF-β expression was not significantly increased (1.50 ± 0.35 fold, P = 0.2766) 10 days after infection, in contrast to the raised expression level in infected WT mice (2.33 ± 0.37 fold, P = 0.0087)." (PMID 22675647, 2012). "Cucurbitacin I or Stattic treatment after infection failed to decrease the number of intracellular F. novicida, indicating that intracellular proliferation was not affected by the inhibitors, indicating that the JAK2/STAT3 pathway is important for the internalization step of F. novicida." (PMID 39255287, 2024).
infection (continued). "Compared to the corresponding protein level measured in uninfected cellular extracts, the infection performed with P. gingivalis at a MOI of 100 significantly reduced the expression level of SOCS-3 (5-fold), IRF-1 (5-fold), and EGFR (6-fold), but not STAT-3, in the nuclear extracts." (PMID 28748038, 2017). "Since BepD of B. taylorii triggered the STAT3 phosphorylation at early time points when expressed in B. henselae, we speculated that other than described for the B. henselae VirB/VirD4 T4SS, the one of B. taylorii was not induced during the first hours of infection." (PMID 35910598, 2022).
hematological malignancies (63 papers, 2009 to 2026). "Aspartic acid 661 (D661) is the second most common frequent STAT3 mutational hotspot, with four variants (D661Y, D661V, D661H and D661N) reported in hematologic malignancies." (PMID 41527523, 2026). "Another critical effect of azacitidine involves the inhibition of NF-κB and STAT3 signaling, both of which are associated with inflammation and cell survival in hematological malignancies." (PMID 40728989, 2025). "The clinical relevance of hyperactive STAT3 has been linked to subsets of hematological malignancies, with the identification of JAK1/3 or STAT3 mutations." (PMID 38573819, 2024). "Somatic mutations in the SH2 domain of STAT3, such as S614R, D661V and D661Y, are known to be activating and prevalent in patients with solid and hematological malignancy." (PMID 36441748, 2022). "In a general framework, hematological malignancies associated with STAT-3 alteration are linked to gain of function (GOF)." (PMID 35990641, 2022). "STAT3 is a gene known to be mutated in various hematological malignancies, and some of the mutations that we found were previously known activating mutations (D661Y and S614R each in one MS patient, Y640F and H410R each in one control)." (PMID 34874980, 2021). "Gain-of–function mutations involving JAK genes have been implicated in activating STAT3 and contributing to the pathogenesis of hematologic malignancies and solid tumors." (PMID 32188095, 2020). "STAT3 mutations suggest the presence of subclinical T-LGL in hematologic diseases." (PMID 37142644, 2023). "We have recently shown that somatic mutations are preferentially detectable in CD8+ cells and that these mutations are especially enriched in the signal transducer and activator of transcription 3 (STAT3) gene and to lesser extent in other genes implicated in hematological malignancies." (PMID 36441748, 2022). "The transcription factor, STAT3 plays a pivotal role in several hematological malignancies by regulating genes that control cell survival, proliferation, and metabolism." (PMID 41502514, 2025). "The STAT3 pathway ATP and Itaconate metabolism are targets for clinical trial development to improve current chemotherapy regimens in hematologic malignancies." (PMID 38555305, 2024). "Expression of JAK1/2 and STAT3 in latently infected cells from both lines was suggestive of an IL-6 response axis (IL6(R)/JAK/STAT3) known to be activated in hematologic malignancies." (PMID 39446925, 2024). "FDA-approved agents for inflammatory diseases targeting the IL-6/JAK/STAT axis are being evaluated together with novel STAT3-specific inhibitors for the treatment of hematological malignancies and solid tumors." (PMID 37509339, 2023). "We hereby report a case with an incomplete form of STAT3 GOF intensified by a concomitant hereditary hematological disease, which misleads the diagnosis." (PMID 33519826, 2021). "Being the most common and specific for this disorder, STAT3 mutation currently remains the genetic marker suggestive of LGLL, whereas STAT5b gene is frequently described mutated also in many other hematologic diseases beyond LGLL." (PMID 32133291, 2020). "The proved underlying mechanisms of the cytotoxic effects of icaritin are different in various cell types of hematological malignancies but associated with the critical cell signal pathway, including PI3K/Akt, JAK/STAT3, and MAPK/ERK/JNK." (PMID 31032347, 2019). "STAT3 (signal transducer and activator of transcription 3) is an oncoprotein involved in many hematological malignancies." (PMID 31065022, 2019). "The JAK2/STAT3 axis is one of the most recognized signaling pathway, whose constitutive activation occurs with high frequency in several hematopoietic diseases and solid tumors." (PMID 31817171, 2019).
hematological malignancies (continued). "In the context of hematological malignancies, the compound has been shown to be a direct inhibitor of STAT3 signaling as it binds to STAT3 near the Tyr 705 phosphorylation site, thereby preventing its dimerization and hence its subsequent signaling cascade." (PMID 30217007, 2018). "Here, we describe some of these synthetic molecules with relevance to their use in hematological malignancies and their ability to act via direct or indirect STAT3 inhibition." (PMID 30217007, 2018). "Few selected pharmacological agents targeted at inhibiting the STAT3 signaling cascade for treating various hematological malignancies are discussed in the following sections." (PMID 30217007, 2018). "This review focuses on the role of STAT3 in pathogenesis i.e., proliferation, differentiation, migration, and apoptosis of hematological malignancies viz." (PMID 30217007, 2018). "CK2 increased protein expression and enzymatic activity has been described to positively regulate the PI3K pathway and STAT3 and NF-κB signaling in hematological malignancies." (PMID 27276707, 2016). "Stat3 is an oncogene and is constitutively active in a number of solid and hematological malignancies." (PMID 24086526, 2013). "The potential for PPARγ agonists as inhibitors of Stat3 and NF-κB survival signaling in hematological malignancies is discussed in Section 2.8." (PMID 20204067, 2010). "STAT3 has been shown to be overactivated in a variety of tumors, including solid tumors and hematological malignancies." (PMID 32714202, 2020). "In that PPARγ agonists inhibit the IL-6-regulated Stat3 signaling cascade, a role for PPARγ agonists in regulating expression of miRNAs critical to the pathogenesis of hematological malignancies may be an important avenue of future scientific investigations." (PMID 20204067, 2010). "Similarly, other post-translational modifications such as oxidation, glutathionylation, or sumoylation were shown to negatively regulate STAT3/5 activity, but their impact on STAT3/5-driven hematologic malignancies are still unknown." (PMID 31963765, 2020). "STAT3, IL5, and TLR4 normalized counts showed similar patterns to NGAL normalized counts in hematological malignancy and control groups." (PMID 34400898, 2021). "A small molecule targeting the SH2 domain of STAT3, OPB-51602, has entered clinical trials for the treatment of hematological malignancies." (PMID 34440253, 2021). "STATs, particularly STAT3 and STAT5, are hyperactivated in various solid tumors and hematological malignancies stimulating cellular proliferation and survival." (PMID 34440253, 2021). "Atovaquone also targets signal transducer and activator of transcription 3 (STAT3), which is actively expressed in many solid and hematological malignancies." (PMID 33028364, 2020). "At the same time, another study evidenced that as an oral inhibitor of STAT3, OPB-51602 can be applied in the treatment of relapsed and refractory hematological malignancies." (PMID 31842997, 2019). "The transcription factors and proto-oncogenes STAT3 and STAT5 are highly activated in hematological malignancies and represent promising therapeutic targets." (PMID 24473086, 2014). "T-cell immunophenotype was CD45+CD3dim+CD5-CD4-CD8+CD7+CD57p+CD25-CD30-, TCRγδ+, transducer and activator of transcripton-3 (STAT3) Y640F mutation and fusion gene NPL-DHX9 rearrangement were confirmed, which has never been reported in hematological diseases." (PMID 35600388, 2022). "Similarly, combining STAT3 inhibitors with epigenetic modulators, such as HDAC inhibitors or DNA methyltransferase inhibitors, has demonstrated efficacy against both solid tumors and hematological malignancies." (PMID 40166646, 2025). "We also examined the frequency of STAT3 and STAT5B mutation in hematologic diseases without T-LGL." (PMID 37142644, 2023).
hematological malignancies (continued). "Therefore, TLR9-targeted delivery of STAT3 inhibitors, as single agents or in combination with T cell-based approaches, offers a novel strategy for safer and more effective immunotherapy of BCL and, potentially, other hematologic malignancies." (PMID 29433938, 2018). "Unlike in other hematologic malignancies, in CLL Stat3 is constitutively phosphorylated exclusively on serine 727 residues, translocates to the nucleus, binds to DNA, and activates the transcription of genes known to be transcribed by tyrosine-phosphorylated Stat3." (PMID 20686606, 2010).